XIST (X inactive specific transcript)
Diseases named in the same sentence as XIST in open-access papers (continued):
Sharing a sentence is not in itself a finding about the gene and the disease.
cancer (continued). "Furthermore, 128 ceRNAs were found to compete with XIST for miRNAs binding and were positively related to XIST across cancers, especially BRCA and UCEC." (PMID 36212008, 2022). "This inconformity resulted in failure to determine whether XIST could become a strong prognostic indicator of cancer patients." (PMID 36212008, 2022). "XIST may act as a novel biomarker for survival and immunotherapy across cancers in the immediate future." (PMID 36212008, 2022). "A functionally similar axis involving XIST, miR-486-5p and neuropilin-2 has also been found to be involved in the epithelial–mesenchymal transition of colorectal cancer cells, thus participating in cancer progression." (PMID 35054794, 2022). "Thus, the expression of XIST is upregulated in a variety of cancers that promotes the occurrence and development of cancer via different mechanisms." (PMID 36035993, 2022). "XIST acts as an oncogene to promote the development of cancer via multiple pathways." (PMID 36035993, 2022). "In this context, lncRNA XIST has been studied in several cancers including NSCLC." (PMID 35453680, 2022). "StarBase discovered that XIST could potentially interact with 29 proteins and 191 miRNAs across cancers." (PMID 36212008, 2022). "Hence, more samples are essential to further researches which will be conducted to verify the prognostic roles of XIST in other cancers." (PMID 36212008, 2022). "The mis‐regulation of XIST has been reported in numerous cancers." (PMID 36116139, 2022). "From starBase, we found 29 proteins interacting with XIST, and identified 4 miRNAs which might be sponged by XIST in cancers." (PMID 36212008, 2022). "However, a potential mechanism of XIST in glucose metabolism disruption in these cancers is yet to be investigated." (PMID 33652661, 2021). "Interestingly, recent studies suggest that high XIST expression levels correlate with a poor survival in various types of cancer." (PMID 33916248, 2021). "Silencing of XIST was performed with siRNA as the cancer function model." (PMID 34733782, 2021). "Moreover, lncRNA XIST has long been recognized as an oncogenic gene and is preferentially expressed in cancers." (PMID 33936212, 2021). "XIST could serve as an oncogene or tumor suppressor, and further studies are still needed to elucidate the roles of XIST in cancer biology." (PMID 34527584, 2021). "In addition, XIST displays an opposite effect in the same cancer, suggesting that XIST controls cancer development at multiple levels." (PMID 34930117, 2021). "Thus, XIST influences the onset and advancement of malignancies, but the mutual action between XIST and AAA advancement has not yet been reported." (PMID 33501488, 2021). "However, in NSCLC and other cancers the oncogenic mechanism of XIST remains incompletely understood." (PMID 32209729, 2020). "Additionally, through targeting the miR-429/ZEB1 axis, XIST also affects morphology of cancer cells, such that silencing XIST results in a change in cell morphology, from the original spindle shape to a rounded one." (PMID 32664703, 2020). "LncRNA X Inactive-Specific Transcript (XIST) is overexpressed in various cancers, suggesting that XIST may function as marker for cancer diagnosis." (PMID 33228517, 2020). "Besides some well-known cancer-associated lncRNAs such as LINC01158, LINC00461, XIST, and HOTAIRM1, we also identified several potential GBM progression-associated lncRNAs like POLR2J4, WWTR1-AS1, and VIM-AS1." (PMID 33505440, 2020). "Also, one common point of XIST’s function in all these cancer cells lines on its regulation towards different kinds of miRNAs." (PMID 30858762, 2019). "Therefore, we aimed to further explore the prognostic value and clinical significance of XIST in various types of cancers." (PMID 29752340, 2018). "This meta-analysis was performed to evaluate the prognostic potential of XIST in malignant tumors." (PMID 29568404, 2018).
cancer (continued). "XIST was correlated with poor prognosis, which suggested that XIST might serve as a novel predictive biomarker for cancer patients, especially for patients of digestive system tumors." (PMID 29752340, 2018). "XIST was involved in pathways related to tumorigenesis and cancer development, thus it had great therapeutic value and might contribute to personalized medicine therapy." (PMID 29752340, 2018). "XIST could function as endogenous miRNA sponges to combine different miRNAs in different types of cancers, thus regulating proliferation, progression, and metastasis of tumors." (PMID 29752340, 2018). "Therefore, the present systematic review and quantitative meta-analysis were performed to assess the prognostic and clinicopathological roles of XIST in different types of cancers and further to evaluate its predictive value in digestive system tumors." (PMID 29752340, 2018). "Many clinical studies have clarified that the expressions of lncRNA XIST not only played an important role in the differentiation, proliferation, and genome maintenance of cells, but also with the development and progression of cancer." (PMID 29556138, 2018). "The result showed that higher lncRNA XIST expression in cancer tissue was related to a worse OS." (PMID 29556138, 2018). "The status of XIST and the exact consequences therein on the Xi still remains unclear and is poorly understood with respect to cancer and requires further investigation." (PMID 29732012, 2018). "XIST expression has been found to be dysregulated in a variety of human cancers when compared to normal cells; meanwhile, the dysregulation of XIST expression can also affect cancer cell proliferation, invasion and migration." (PMID 29371940, 2017). "While XIST localization in cancer cells and stem cells is clearly important, the majority of normal differentiated cells appear to have redundant or complex mechanisms to faithfully anchor XIST to Xi." (PMID 28947659, 2017). "Pan-cancer analysis showed that XIST was down-regulated in a wide range of cancers." (PMID 29212233, 2017). "Some well-known cancer-associated lncRNAs, such as H19, XIST, HOTAIR, MALAT1, MEG3, HNF1A-AS1 and PVT1, have indicated oncogenic and/or tumor suppressive roles like protein-coding genes in various cancers." (PMID 27074572, 2016). "It was found that lncRNA XIST is dysregulated in different cancers." (PMID 27620004, 2016). "Such samples might reflect technical problems, but could also be due to true biological effects; for example,XIST expression is altered in some cancers and in early stages of development." (PMID 27746907, 2016). "The ability of XIST to induce gene silencing in somatic cells has important implications for cancer cells where rearrangements or reactivation of XIST may bring previously active genes under the influence of XIST." (PMID 26429547, 2015). "Putative cancer drivers with a propensity to carry clonal SCNAs were an android receptor gene, the RNA gene XIST, the BRCA1 binding partners RBBP7 and NCOA2, a BRCC3 metaloprotease unit of the BRISC complex and CSTF2 that prevents inappropriate RNA processing at sites of DNA repair." (PMID 26632267, 2015). "Also, the expression of XIST correlates with disease-free survival of Taxol-treated cancer patients." (PMID 23887658, 2013). "However, the observation of inappropriate XIST expression/localization in cancer cells sheds light on a possible new mechanism of breast carcinogenesis." (PMID 19440381, 2009). "In our previous study, cancer‐derived exosomes carrying XIST may activate neurons to secrete GDNF." (PMID 40985319, 2025). "In further support of the MUC1-C/XIST pathway, we found that MUC1-C and XIST regulate common genesets associated with activation of (i) miRNAs, such as miR-21, (ii) lncRNAs NEAT1 and MALAT1, and protein encoding genes that are linked to inflammation and dysregulated in cancer." (PMID 38740827, 2024).
cancer (continued). "However, accumulating evidence suggests that XIST can be detected in male cells as well, and it participates in the development of cancers and other human diseases by regulating gene expression at epigenetic, chromatin remodeling, transcriptional, and translational levels." (PMID 39639337, 2024). "There is no known association of MUC1-C and XIST in promoting cancer progression." (PMID 38740827, 2024). "In addition to transcription factors, in AML samples, we identified the upregulation of genes that were reported to accelerate leukaemogenesis, including S100A8, S100A9, and RPS26, and the downregulation of genes related to cancer control and defence, such as XIST, GIMAP7, NKG7, and GNLY." (PMID 37615858, 2024). "Therefore, we believe that XIST may play a cancer‐suppressing role in HCC and contribute partially to the sex difference of HCC due to different liver expressions in different sexes." (PMID 38148658, 2023). "However, further studies need to be performed to confirm whether these proteins can cooperate with XIST to affect biological behaviors and epigenetic pathways of cancers." (PMID 36212008, 2022). "Interestingly, XIST exhibits contradictory functions in different cancers as well." (PMID 35723009, 2022). "In these four cancers, XIST promoter methylation was negatively correlated with XIST expression, which indicated that methylation of XIST promoter might contribute to down-regulated expression of XIST in cancers." (PMID 36212008, 2022). "This indicates that the expression of XIST may be related to TSCC cancer development." (PMID 34295808, 2021). "However, in two instances XIST deletion is seen to provoke cancer." (PMID 33664771, 2021). "Moreover, XIST and miR-191-5p expression levels were negatively correlated in cancer tissues." (PMID 33942699, 2021). "When XIST gene was silenced in two different cell lines (of male and female origin), a number of genes were differentially expressed; playing a role in signal transduction pathways, energy balance and metabolism, thus providing a better insight of the role of this lncRNA in cancer." (PMID 33255394, 2020). "In addition, it has been reported that the level of lncRNA XIST in many cancer patients is reduced." (PMID 31384173, 2019). "Moreover, the oncogenic role of XIST in cancers has been well-established." (PMID 30463570, 2018). "These discoveries indicate that XIST may be a potential prognostic biomarker for human cancers." (PMID 29568404, 2018). "Dysfunctional expression of XIST may have a pathological role in cancer." (PMID 27911852, 2017). "Hence, XIST might have context-dependent pro- or antitumor functions in human cancers and it would be interesting to know, if chemical modifications in XIST can shift the balance in one or the other direction." (PMID 29125541, 2017). "In addition to XIST, the role of miR-29c in cancers has been extensively studied." (PMID 28831025, 2017). "Finally, a ceRNA role in cancer was also reported for XIST (X-inactivate specific transcript)." (PMID 29147648, 2017). "XIST, a class of lncRNA is associated to both sex and non-sex related cancers." (PMID 30159409, 2016). "Together, our analysis shows that XIST loss is associated with transcriptional changes of the X chromosome and autosomes in human cells, and distinct upregulation of X-linked genes is only observed in human embryonic stem cells but not in lineage-specific or cancer cells." (PMID 40981384, 2025). "X-inactive-specific transcript (XIST), a common oncogene in various cancers, was reported to be aberrantly upregulated in OA tissue specimens and generated the pro-inflammatory effect, indicating the involvement of XIST in OA pathogenicity." (PMID 40420260, 2025). "A recent study revealed that XIST activates the IL-6/STAT3 pathway to promote inflammation and cancer stem cell self-renewal." (PMID 40407589, 2025).
cancer (continued). "Extensive research has been conducted on the role of METTL16 in regulating cancer progression through m6A modification of target genes, including U6 snRNA, MALAT1, XIST, and RAB11B‐AS1, and mRNA (MAT2A, VPS33B, FGFR4, and GPX4)." (PMID 40095756, 2025). "The present results indicate that the MUC1-C/XIST pathway in somatic cells may also contribute to the establishment of inflammatory memory, which is essential for protection of barrier tissues and has been co-opted by cancer cells in driving the CSC state, DNA damage resistance and immune evasion." (PMID 38740827, 2024). "Emerging evidence indicates a significant role of lncRNA XIST/EZH2/Klf2 axis in promoting cell proliferation and cancer aggressiveness." (PMID 39639337, 2024). "Emerging evidence suggests that XIST and STAT3, by mutually regulating each other, form a double positive feedback loop that promotes inflammation and cancer development." (PMID 36922677, 2023). "The relative XIST expression level in serum was detected using U6 as a standard and was positively correlated with HIF-1a expression levels in cancer tissues (P<0.001)." (PMID 37036874, 2023). "XIST expression was potently downregulated in SRC-1 knockdown-cells, whereas expression of XIST was increased in SRC-1 overexpressing cancer cells." (PMID 36903477, 2023). "XIST was shown to be overexpressed in NSCLC and mediates an important pathway of EMT regulation in this cancer." (PMID 37686426, 2023). "Concretely, XIST expression was decreased significantly in CESC, COAD, OV, READ, STAD, UCEC and UCS; but it was up-regulated in five cancers, including ACC, DLBC, LUAD, TGCT and THCA." (PMID 36212008, 2022). "While XIST RNA is required for X chromosome inactivation (XCI), it can also suppress cancer in vivo." (PMID 36116139, 2022). "Particularly, XIST was down-regulated and predicted a good prognosis in BRCA, COAD and OV, but its expression was inconsistent with outcomes in other cancers." (PMID 36212008, 2022). "To investigate the immunoregulatory mechanism of XIST, we investigated more than 40 common immune checkpoint markers in TIMER 2.0 across cancers." (PMID 36212008, 2022). "Previous studies discovered that XIST and its downstream regulators were correlated with TIME and PD-L1 expression, and played critical roles in invasion and metastasis of cancers." (PMID 36212008, 2022). "This present research found that XIST was related to infiltration levels of T cell CD4+, Tregs, mast cell, Th1, macrophage and T cell NK in more than 8 types of cancers." (PMID 36212008, 2022). "AC10889.1, TTTY15, XIST, AC006157.1, PAX8-AS1, SNHG25, and JPX were mainly involved in cancer development." (PMID 33924951, 2021). "By competitively binding with miR-140, a variety of lncRNAs, such as lncRNA XIST, lncRNA MALAT1 and lncRNA H19, can promote cancer progression via facilitating the proliferation, migration and invasion of cancer cells in vitro and metastasis in vivo." (PMID 34496800, 2021). "Specifically, we analyzed the role of five lncRNAs (BBC3, STK11IP, XIST, FDFT1, and PRR14), which are known to be related to cell growth and apoptosis in cancer development." (PMID 34295808, 2021). "XIST, a lncRNA, regulates X chromosome inactivation (XCI), and plays a crucial role in the development of numerous cancers." (PMID 34295808, 2021). "Glucose transporters (GLUTs) as important modulators of glucose utilization which are commonly dysregulated in cancer, have been shown to be targeted by several lncRNAs such as LINC01638, Ftx, XIST, YIYA (LINC00538), HISLA, AWPPH, and UCA1." (PMID 33123468, 2020). "As a result, the hub-hub subnetwork was composed of all these hubs and their 103 edges, including the known cancer-related lncRNAs MALAT1 and XIST." (PMID 32802855, 2020). "We also detected a strong reduction of XIST, NEAT1 and MALAT1, three conserved nuclear lncRNAs with well-known links to a broad range of cancer types." (PMID 32727085, 2020).
cancer (continued). "Additionally, since the loss of inactive X chromosome is a frequent event in cancer cells, the absence of XIST expression may be a marker for genetic instability correlated with drug resistance." (PMID 27664137, 2017). "Furthermore, real-time PCR analysis showed knockdown of lncRNA XIST could markedly decrease the expression of many stemness-associated genes (Nanog, Oct-4 and SOX2) and surface antigens associated with cancer stem cells (CD24, CD44, CD133, CD155 and CD166) (*P<0.05)." (PMID 28837144, 2017). "It has been shown that various lncRNAs, such as LINC00511 or XIST, served as a modular scaffold of EZH2/PRC2 complexes and interacted and coordinated their localization, thereby contributing to cancer progression." (PMID 29228709, 2017). "Among these, XIST, CDKN2B-AS1, CRNDE, TUG1, SOX2-OT, etc. have been reported playing crucial roles in inflammation pathway of cancer progression." (PMID 27809873, 2016). "Some well-known cancer related lncRNAs such as H19, PVT1 and XIST all regulated the ‘negative regulation of cell proliferation’ process across different cancers." (PMID 27580177, 2016). "When PanIN samples were compared to PDACs, the most commonly up-regulated genes in the cancers were POSTN, COL1A2, SULF1, FN1, IGHM, VCAN and XIST, and these down-regulated were PGC and PPY." (PMID 23372777, 2013). "Our observations sheds light on a possible previously uncharacterized mechanism of breast carcinogenesis mediated by XIST misbehaviour, particularly in BRCA1-related cancers." (PMID 19440381, 2009). "At the same time, in various cancer types including NSCLC, XIST functions as an oncogene." (PMID 37686426, 2023). "Furthermore, NEAT1, MALAT1, XIST, and PKD had reported or validated having a close relation with pro chemotherapy resistance of malignant tumors." (PMID 35873473, 2022). "Given the multiple mechanisms of action known for lncRNAs, it is not surprising that the same lncRNAs may exert dual functions in cancer, acting as either tumor suppressors or oncogenes, depending on the cancer type (H19, BANCR, TINCR, MALAT, XIST)." (PMID 35159386, 2022). "XIST, which is the core of XCI, plays a key role in many cancers." (PMID 36035993, 2022). "In addition, IHC staining exhibited that the Ki67 (a marker of proliferation) was upregulated while GRP78 was down-regulated by KCNQ1OT1/XIST, suggesting that KCNQ1OT1/XIST promoted cancer cell proliferation but inhibited ERS activation." (PMID 34521445, 2021). "Accumulating lines of evidence have proven that lncRNAs could be targets for cancer diagnosis and may be suitable biomarkers, such as HOTAIR, H19, and XIST." (PMID 32785606, 2020). "Functional data about how XIST participates in cancer pathology are not enough, and further studies are needed." (PMID 32038997, 2019). "Expression of XIST was significantly upregulated in cancer tissues compared with that in non-tumorous tissues." (PMID 29100288, 2017). "In fact, XIST is functionally compromised or mislocalized and the Barr body is not observable in some cancers." (PMID 28947659, 2017). "There was a very high-degree of commonality across all the models, with three Y-chromosome genes selected across all 17 cancers (ZFY, EIF1AY, and DDX3Y), RPS4Y1 (also on the Y-chromosome) selected across 15 of 17 cancers, and XIST (on the X-chromosome) selected across 14 of 17 cancers." (PMID 26755347, 2016). "Our study provides the first evidence of the regulatory mechanisms of the newly identified lncRNA XIST/miR-101/EZH2 axis in carcinogenesis and metastasis, which may shed light on their targeted applications in cancer therapies." (PMID 27620004, 2016). "In conclusion, our study provides further evidence that BRCA1 is not involved in XIST localization and demonstrate that the detection of XIST in a cancer cell is not indicative of the presence of an inactive X chromosome." (PMID 19440381, 2009).